SERPINB3 (serpin family B member 3)
Diseases named in the same sentence as SERPINB3 in open-access papers (continued):
Sharing a sentence is not in itself a finding about the gene and the disease.
tumor (continued). "Additionally, in vitro data have shown that SerpinB3 promotes the EMT and increases cell proliferation and invasiveness, while oncogenic Ras upregulates SerpinB3/4 expression, leading to NF-kB activation, IL-6 production and tumor growth." (PMID 38201652, 2024). "SERPINB3 tumors show accumulated myeloid cells and increased tumor growth." (PMID 37279067, 2023). "Targeting SERPINB3 reprogrammed the immunosuppressive environment and sensitized the tumor to RT." (PMID 37279067, 2023). "Furthermore, SERPINB3 protein was detected in both the nucleus and the cytoplasm of tumor cells by immunohistochemistry (IHC)." (PMID 37980563, 2023). "These same tumor types have high levels of SERPINB3 expression." (PMID 37279067, 2023). "However, upregulation of SERPINB3 did not alter primary tumor growth of AsPC-1 cells, as indicated by the comparable tumor weights in the SERPINB3-expressing and control cells." (PMID 37980563, 2023). "Similarly, when we depleted CD11b+ myeloid cells in SERPINB3 tumors, we observed initial tumor growth inhibition and improved T cell activity." (PMID 37279067, 2023). "We sought to understand the potential of targeting SERPINB3 in tumor growth inhibition and whether combination with RT could enhance antitumor immunity." (PMID 37279067, 2023). "Thus, we felt it important to understand the impact of SERPINB3-KO on tumor cells of both HPV-positive and HPV-negative origins." (PMID 35022555, 2022). "These clinical observations raise the intriguing possibility of exploiting the discovery of small-molecule inhibitors that incapacitate specific serpins to enhance the response of SERPINB3-expressing tumor cells to cancer therapeutics, irradiation, or lysoptosis inducers." (PMID 35022507, 2022). "Since the FIECs are a fastidious system, we turned to human tumor cell lines null for SERPINB3 to determine whether the predominance of lysoptosis was reproducible even after appropriate activation of another RCD." (PMID 35022507, 2022). "Similarly, PFGS combined with Sor treatment significantly downregulated the expression of NF-κB, HIF-2α, and SerpinB3 in the tumor compared with a single treatment." (PMID 36285158, 2022). "Indeed, SERPINB3 has been shown to be a negative regulator of programmed cell death in tumor cell lines in response to cytotoxic drugs and ionising radiation." (PMID 26799424, 2016). "Moreover, SERPINB3/4 have been recently shown to be up-regulated by oncogenic Ras and to be able to promote NF-kB-related inflammatory cytokine production favoring tumor progression." (PMID 25544768, 2015). "At the inferential level, we propose that the convergence of epithelial SERPINB3-associated programs and stromal immune mimicry may represent one mechanism through which immune activation fails to translate into durable tumor control." (PMID 41595458, 2025). "Furthermore, IHC of the endothelial marker CD31 and the reactive oxygen species (ROS) marker 8-hydroxy-2′-deoxyguanosine (8-OHdG) revealed that angiogenesis and oxidative stress are upregulated in the tumor xenografts of SERPINB3-overexpressing AsPC-1 in the orthotopic model." (PMID 37980563, 2023). "Therefore, targeting SERPINB3 may be an alternative approach to reduce tumor growth and provide therapeutic potential." (PMID 37279067, 2023). "Considering the increasing number of studies reporting the association of SERPINB3 with tumorigenesis, metastasis, prognosis, and recurrence, additional roles of SERPINB3, independent of proteinase-inhibitory activity, in tumor progression and resistance to therapy are likely." (PMID 37279067, 2023). "Here, we identified an association between SerpinB3 positivity and tumor size in the DEN-HCC rat model as well as a negative correlation between SerpinB3 and caspase-3 mRNA levels in human HCCs, highlighting the contribution of SerpinB3 to the malignant phenotype and tumor progression of HCC." (PMID 30717317, 2019).
tumor (continued). "We also observed the enrichment of CDKN2A (p16), SERPINB3, KRT5, and TP63, which are well‐established biomarkers for HPV‐positive neoplasia and are typically expressed in tumour areas." (PMID 41362277, 2026). "By the GEPIA platform, we conducted an expression analysis at the RNA level and discovered significant upregulation of SERPINB3, LY6D, DCBLD2, and ANLN within PC tumor tissues." (PMID 41427028, 2025). "First, we selected 10 pairs of BC tumor and cancer-adjacent normal tissues to verify COMP and SERPINB3 gene expression by real-time PCR." (PMID 37965307, 2023). "Given that lymphocyte-mediated immune activity plays a role in tumor response to RT and that RT is known to reshape the TME, the SERPINB3-mediated TME and its response to radiation was characterized in an immunocompetent murine model." (PMID 37279067, 2023). "In this study, we revealed that SERPINB3 modulated the TME toward an immunosuppressive phenotype by upregulating CXCL1/8 and S100A8/A9 production to facilitate tumor growth and impede the success of RT." (PMID 37279067, 2023). "The effects of PFGS combined with Sor on tumor growth and apoptosis and the expression of NF-κB, HIF-2α, and SerpinB3 in tumor tissue were assessed." (PMID 36285158, 2022). "Moreover, mutations in SERPINB3 (16% vs. 3%, p < .001) and SERPINB4 (13% vs. 4%, p < .01) were more frequent in high ITS than low ITS group, which might promote serpin protein misfolding to increase tumor immunogenicity." (PMID 32969604, 2020). "As a consequence of the inhibition of proteasomal/lysosomal protein degradation, SERPINB3/B4 have been reported to induce the PERK and ATF6α arms of the UPR in a large variety of tumor cells." (PMID 31151143, 2019). "A significant increase in SerpinB3 expression levels was found in more advanced stages (III-IV), both in tumor and non-tumor samples, although absolute values were higher in tumor specimens." (PMID 28178650, 2017). "Low SERPINB3 and SERPINB4 expression was correlated with prolonged PFS, accompanied by the significant downregulation of gene sets involved in DNA replication, nonsense-mediated mRNA decay, and protein translation in long-PFS tumours." (PMID 42079393, 2026). "Furthermore, we analyzed the protein expression levels of ANLN, DCBLD2, LY6D, and SERPINB3 using the UALCAN platform, which were notably upregulated within PC tumor tissues." (PMID 41427028, 2025). "SerpinB3 expression increases in response to Tumor Necrosis Factor (TNF)-α and Ras-driven inflammation leading to NF-kB activation, IL-6 production and tumor growth." (PMID 39061218, 2024). "In conclusion, high levels of SerpinB3/4 in tissue and serum in CCA are associated with poor outcomes after surgery, regardless of tumor subclass." (PMID 38201652, 2024). "Of note, SerpinB3 and TGF-beta expression have been related to the WNT-beta-catenin pathway activation in patients with HCC and those with this particular pattern presented earlier tumour recurrence and worse prognosis." (PMID 37509293, 2023). "Additionally, SERPINB3 can protect cancer cells from oxidative stress through the up-regulation of HIF-1α transcription and HIF-2α stabilization to favor tumor growth." (PMID 33562077, 2021). "Tumor specimens positive for these pathologic parameters had significantly higher expression of SerpinB3, COX-2 and β-Catenin, compared to negative ones." (PMID 28178650, 2017). "Our results have demonstrated that SerpinB3, COX-2 and β-Catenin were significantly higher in tumor tissues, compared to the normal counterpart and that their expression progressively increased according to tumor stage." (PMID 28178650, 2017). "Tumor and non-tumor samples differed significantly in the expression of 10/22 genes: CCNB1, CLDN4, CLDN6, MMP2, MUC1 (all: p < 0.05), BAG1, SERPINB3 (all: p < 0.01), CD44 (standard variant), MKI67, and MYBL2 (all: p < 0.001)." (PMID 27542596, 2016).
tumor (continued). "As expected, we found that gene expression patterns are different in PC tumor samples compared to normal, undiseased peritoneum with a number of genes differentially regulated: BAG1, CCNB1, CD44, CLDN4 and 6, MMP2, MKI67, MUC1, MYBL2, and SERPINB3." (PMID 27542596, 2016). "Moreover, images from human HCC specimens indicate that positive stain for HO-1, a protein which is known to be expressed in a redox-sensitive way in tissues undergoing generation of ROS, was detected in the same tumor areas positive for HIF-2α and SERPINB3." (PMID 25544768, 2015). "To examine whether TMEM65 promotes TNBC progression via regulating SERPINB3, we stably reintroduced SERPINB3 into TMEM65‐depleted SUM159PT and Hs578T cells, and then we carried out in vitro experiments and xenograft tumor growth assays in vivo." (PMID 40546127, 2025). "In conclusion, the present study provides evidence that SerpinB3/4, both in the serum and in tumoral tissue, could be considered a useful biomarker to identify the small subgroup of CCA patients with more aggressive tumor biology and dismal prognosis." (PMID 38201652, 2024). "Our findings that SERPINB3 modulated the crosstalk between immune cells and cancer cells via secretion of CXCL1/8 and S100A8/A9 implicate this protease inhibitor member of the SERPIN superfamily in a key tumor strategy of evading antitumor immune responses and resisting therapies such as radiation." (PMID 37279067, 2023). "We found that PFGS effectively enhanced the inhibitory effect of Sor on tumor proliferation and invasion and promoted tumor apoptosis, resulting in a significantly increased antitumor effect of Sor in vivo and in vitro by suppression of the NF-κB/HIF-2α/SerpinB3 pathway." (PMID 36285158, 2022). "As expected, the tumor sample population showed higher expression levels of pro-mitotic genes such as CCNB1 and MYBL2, genes that modulate the host immune response, such as SERPINB3, and the tight-junctions proteins claudin-4 and claudin-6, which are often deregulated in cancers." (PMID 27542596, 2016). "Indeed, although its precise in vivo role has not been identified yet, SERPINB3 has been reported in vitro to protect tumor cells from induction of apoptosis and to induce epithelial-mesenchymal transition (EMT) and increased invasiveness as well as cell proliferation." (PMID 25544768, 2015). "Functional studies demonstrated that SERPINB3 overexpression (but not the RCL-deleted mutant, SERPINB3△6) promotes LUAD cell proliferation and tumor growth, with NPM1 sumoylation being critical for this oncogenic effect." (PMID 41444337, 2025). "The results showed an up-regulation of SerpinB3 in HCC tissues with respect to matched surrounding non-tumor samples and a down-regulation of miR-122 in HCC compared to non-tumor samples." (PMID 30717317, 2019).
cancer (64 papers, 2011 to 2026). A tumor composed of atypical neoplastic, often pleomorphic cells that invade other tissues. "SERPINB3 encodes a serine protease inhibitor implicated in modulating apoptosis, inflammation, and immune evasion in various cancers, making it a compelling candidate for targeted therapy in TNBC." (PMID 41595458, 2025). "SerpinB3 upregulation has been associated with a number of cancers and autoimmune disorders." (PMID 40779003, 2025). "t has been reported that SERPINB3 confers resistance to drug-induced apoptosis by inhibiting lysosomal cathepsin proteases in cancer cells." (PMID 40297811, 2025). "Using a bi-volcano framework to isolate genes consistently enriched in TNBC relative to ER+ and HER2+ tumors, we identified SERPINB3 as a uniquely upregulated cancer epithelial marker, which we validated in clinical METABRIC tumors." (PMID 41595458, 2025). "Third, TMEM65 acts as a novel regulator of TNBC stemness by activating the OXPHOS‐ROS‐HIF1α‐SERPINB3 pathway to promote cancer progression and chemoresistance." (PMID 40546127, 2025). "For example, serpinA1 (α1-antitrypsin) is upregulated in tumor cells, promoting cancer by inhibiting apoptosis, suppressing immune responses, and stimulating proliferation; while serpinB3 (SCCA1) is a marker of advanced cSCC disease stages." (PMID 40868818, 2025). "Recent studies have described the therapeutic potential of targeting SerpinB3 through its upstream regulators, offering novel strategies for cancer treatment development." (PMID 39061218, 2024). "SerpinB3, a serine protease inhibitor, was recently found to play a relevant role in malignant transformation in different cancers." (PMID 38201652, 2024). "In glioblastoma, SerpinB3 was found to drive cancer stem cell survival, whereas in breast and ovarian cancer, it promotes oncogenesis and resistance to chemotherapy." (PMID 39061218, 2024). "We analyzed 123 resected human CCA tumors to evaluate the expressions of SerpinB3/4 in the cancer cell compartments." (PMID 38201652, 2024). "Our study also presents several potential therapeutic combinations, such as the use of RT with STAT inhibitors or with immune checkpoint blockade, to further improve treatment responses for cancers with elevated SERPINB3 expression." (PMID 37279067, 2023). "To continue our investigations into the role of the metabolites that are involved in the SERPINB3 and basal-like/squamous subtype, we performed a global metabolome analysis of 116 cancer-related metabolites with absolute quantitation." (PMID 37980563, 2023). "Recent studies have identified SerpinB3 as a new immunomodulator in different cancers, including HCC." (PMID 37509293, 2023). "Some studies have documented an important role of SERPINB3 in the modulation of programmed cell death by different mechanisms, both in inflammatory processes and in cancer." (PMID 37965307, 2023). "SerpinB3 is a serine protease inhibitor that plays a relevant role in disease progression and cancer by increasing fibrosis, cell proliferation, and invasion, besides conferring resistance to apoptosis." (PMID 37238609, 2023). "Compared with expression in adjacent tissues, the expression of COMP and SERPINB3 is all upregulated in cancer tissues." (PMID 37965307, 2023). "Our study demonstrated that PFGS synergistically increased the antiliver cancer effects of Sor by lowering activation of the NF-κB/HIF-2α/SerpinB3 pathway." (PMID 36285158, 2022). "Conversely, in cancer disease SERPINB3 was found to inhibit apoptosis, circumventing the mechanism of cell death and favouring tumour growth and metastization." (PMID 25133778, 2014). "In previous studies, SERPINB3 was found to regulate programmed cell death by different mechanisms in various cancers and its over-expression was characteristic of cancerous cells of epithelial origin." (PMID 23185467, 2012).
cancer (continued). "After that we compared SERPINB3 expression among normal and cancer cells of ovaries from laying hens, human EOC cell lines (OVCAR-3 and SKOV-3) and a human ovarian teratocarcinoma cell line (PA-1)." (PMID 23185467, 2012). "To date, a role for SerpinB3/4 has been documented in many different types of human cancer." (PMID 38201652, 2024). "While we are currently investigating the possibility, it remains unclear if other cancer subtypes expressing SERPINB3 are protected against radiation in a similar manner." (PMID 35022555, 2022). "It should be noted that the HT-29 cell line, overexpressing SerpinB3, shows enrichment of cancer stem cell markers and this could be one of the possible explanations for its increased aggressiveness and/or its increased expression of SerpinB3." (PMID 28178650, 2017). "Besides the role in cancer and autoimmunity, SERPINB3 and B4 have a dual role in the immune response to pathogens." (PMID 25133778, 2014). "The high expression of SerpinB3 in these neoplastic cells was also associated with an increase in phosphorylated STAT3, further leading to an immunosuppressive environment through cell-intrinsic and -extrinsic mechanisms as in other cancer types (head and neck, lung)." (PMID 39061218, 2024). "Thus, IL-22 may play a role in the attenuation of drug-induced apoptosis by the increasing the expression of SERPINB3/B4 in cancer cells." (PMID 22922995, 2012). "Our present study shows that IL-22 affects several important functions of OSCC cells via the STAT3-dependent and/or -independent pathways, suggesting that IL-22 may play a role in carcinoma cell differentiation and the upregulation of SERPINB3/B4, well-known biomarkers for SCC." (PMID 22922995, 2012). "The role of SerpinB3 in carcinogenesis includes the induction of EMT, the ability to inhibit cell death by preventing cancer cell apoptosis by either inhibiting JNK or P38 mitogen-activated protein kinase (MAPK) and/or suppressing mitochondrial ROS generation." (PMID 39061218, 2024). "This is due to the direct interaction between TMEM44‐AS1 and SerpinB3, which facilitates the binding of SerpinB3 to downstream targets, leading to the activation of the EGR1/IL‐6 signalling pathway and the subsequent promotion of cancer progression." (PMID 39690143, 2024). "Studies have found that SERPINB3/SERPINB4 can promote the migration and invasion ability of cancer cells, and participate in the process of cell aging and inflammatory response." (PMID 36999136, 2023). "As a matter of fact, among clade B serpins, SERPINB3 and SERPINB5 are well studied by various cancer researchers." (PMID 25020046, 2014). "As it has been documented that SERPINB3 regulates cancer stemness, we next examined whether TMEM65 affects TNBC stemness via SERPINB3." (PMID 40546127, 2025). "To address this, we input the TNBC-exclusive cancer epithelial gene set identified from the scRNA-seq analysis into the STRING protein–protein interaction database and generated a SERPINB3-centered interaction network." (PMID 41595458, 2025). "Additionally, the promising findings regarding the therapeutic potential of targeting SerpinB3 through its upstream regulators, such as PAR2, suggest new opportunities for the development of novel treatment modalities in cancer and in PAR2-induced diseases." (PMID 39061218, 2024). "In this regard, SERPINB3 (clade B member; MIM 600517) represented an ideal candidate, as SERPINB3 is expressed in normal epithelial cells and overexpressed in various damaged cell types, including hepatocytes and cancer cells." (PMID 36833193, 2023).
infection (4 papers, 2013 to 2022). The state of being infected such as from the introduction of a foreign agent such as serum, vaccine, antigenic substance or organism. "Additionally, we constructed SERPINB3‐overexpressing HNSCC cells by lentiviral infection and verified the enhancement of cisplatin resistance and DNA damage repair." (PMID 36382555, 2022). "Also, consistent with mRNA measurements, SerpinB3 was detectable in S. Typhimurium-infected cells late (20 hs) in infection, but was undetectable in cells infected with S. Typhi at any time after infection." (PMID 28742135, 2017).
infectious disease (1 paper, 2014). A disorder directly resulting from the presence and activity of a microbial, viral, or parasitic agent in humans. "Furthermore, the retention of SERPINB3 and B4 duplicates in the H. sapiens, P. troglodytes and G. gorilla clade could have a selective advantage in host-pathogen interactions due to an adaptive response against infectious diseases in Africa, during the evolution of great apes." (PMID 25133778, 2014).
metabolic disorders (1 paper, 2024). "SerpinB3 is a serine-protease inhibitor deeply involved in tissue homeostasis both in physiological and pathological conditions, from tissue repair and immune modulation to carcinogenesis and metabolic disorders." (PMID 39061218, 2024).
neurodegenerative disease (1 paper, 2024). A disorder of the central nervous system characterized by gradual and progressive loss of neural tissue and neurologic function. "Since it has been recently shown that the anti-protease activity of SerpinB3 exerts an important role in PAR2 activation and increased synthesis in metabolic-associated liver disease, we have assessed whether this also occurs in our model of neurodegenerative diseases." (PMID 39062196, 2024).